NR3C2 (nuclear receptor subfamily 3 group C member 2)
Diseases named in the same sentence as NR3C2 in open-access papers (continued):
Sharing a sentence is not in itself a finding about the gene and the disease.
colorectal cancer (11 papers, 2010 to 2025). A primary or metastatic malignant neoplasm that affects the colon or rectum. "NR3C2 is a mineralocorticoid receptor gene encoding mineralocorticoid receptor (MR) that has been considered a tumor suppressor in colorectal cancer, which is consistent with our study." (PMID 34322151, 2021). "The nuclear receptor NR3C2 induces SIRT1 expression in colorectal cancer (CRC), forming an effective NR3C2–SIRT1 axis." (PMID 41425553, 2025). "MR downregulation in colorectal cancer was correlated with increased expression of the VEGF receptor, indicating that NR3C2 exerted specific role in decreasing angiogenesis in tumor." (PMID 34322151, 2021). "We aim to investigate the roles and mechanisms of NR3C2 in colorectal cancer (CRC)." (PMID 36950803, 2023). "We revealed that quercetin, stigmasterol, kaempferol, baicalein, and acacetin played a critical role in colorectal cancer by affecting PTGS2, NR3C2, CA2, and MMP1." (PMID 34125845, 2021). "For instance, NR3C2 presented as a favorable CRC prognosis factor in literature, which is in line with our analysis, though its function in colorectal cancer is still unclear." (PMID 34094897, 2021). "NR3C2, CA2, and MMP1 were identified as key target proteins in another network pharmacological pharmacology analysis of the colorectal cancer." (PMID 34381520, 2021).
hepatocellular carcinoma (11 papers, 2016 to 2025). A malignant tumor that arises from hepatocytes. "Nie and his colleagues demonstrated that NR3C2 suppresses the progression and Warburg effects of hepatocellular carcinoma." (PMID 36950803, 2023). "Another report suggests that miR-766 targets NR3C2 and promotes hepatocellular carcinoma progression by increasing the β-catenin signaling pathway." (PMID 36358691, 2022). "In recent years, many studies have found that NR3C2 serves as a tumor suppressor in many cancers, including hepatocellular carcinoma." (PMID 33996909, 2021). "A recent study demonstrated that miR-766 directly targets the MR gene NR3C2, thus promoting proliferation and metastasis in hepatocellular carcinoma." (PMID 38255942, 2024). "NR1I2, ESR1, ALPL, MME, IGF1, NR3C2 and PTGS2 were differentially low expressed in hepatocellular carcinoma tissues." (PMID 38842135, 2024). "In addition to HK2 and LDHA, some researchers discovered that NR3C2 inhibits cellular aerobic glycolysis by regulating PKLR, an isozyme of pyruvate kinase, in hepatocellular carcinoma cells." (PMID 36950803, 2023).
prostate carcinoma (11 papers, 2008 to 2026). A carcinoma that arises from epithelial cells of the prostate gland. "Since they are co-interacting with PARM1 and MYEF2, ESR1 and NR3C2 may also participate in prostate cancer along with the existent/potential targets." (PMID 25151146, 2014).
colon carcinoma (10 papers, 2013 to 2025). "The expression of NR3C2 in human colon cancer cell lines including HCT116, DLD‐1, RKO, SW480 and SW620 cells was detected." (PMID 36950803, 2023). "The mRNA expression of NR3C2 was significantly decreased in all five colon cancer cell lines compared with the paracancerous tissues." (PMID 36950803, 2023). "Accordingly, the expression of NR3C2 was lower in both colon cancer and rectum cancer than in paracancerous tissues." (PMID 36950803, 2023). "NR3C2, a nuclear transcription factor encoding the MR protein, via the AKT/ERK signaling pathway, inhibits the proliferation, migration, and invasion of colon cancer cells." (PMID 36532065, 2022). "A recent study demonstrated that NR3C2 suppresses colon cancer progression by inhibiting the AKT/ERK pathway." (PMID 36110953, 2022). "Besides, previous studies have illustrated that downregulation of NR3C2 gene and its protein MR leads to poor prognosis in lung and colon cancer." (PMID 32280303, 2020). "Besides, database analysis found that promoter hypermethylation may be the reason for NR3C2 low expression in colon cancer." (PMID 36950803, 2023). "By regression analysis, 6 immune-related DEGs (AEN, F2RL1, NR3C2, PPARGC1A, LGALS4, and XDH) were identified as potential prognostic factors, of which AEN, LGALS4, and XDH were used to construct a risk score model, which can effectively predict overall survival (OS) in colon cancer patients." (PMID 36589748, 2022). "Among the five colon cancer cell lines, RKO and HCT116 cells exhibited a relatively lower expression of NR3C2, while DLD‐1 cells exhibited a relatively higher expression of NR3C2." (PMID 36950803, 2023). "Additionally, NR3C2 is regulated by NCOA1, and this intensified regulation activates the Wnt/β-catenin signaling pathway, enhancing the invasion of colon cancer cells." (PMID 40585960, 2025). "For the top colon cancer MEGs, the consistent tumor suppressor genes included MAP2K4, MAPK10, RUNX3, WNK2 (the four genes were identified by the TSGene 2.0 database), BECN1, FASN, NAT1, and NR3C2." (PMID 33273919, 2020). "Therefore, although TF E2F7 display opposite regulation effect on GFRA1 when comparing with NR3C2 and NR3C1, it did not have a competitive role with them in colon cancer." (PMID 32849837, 2020).
Cerebral ischemia (8 papers, 2012 to 2024). Restriction of arterial blood supply to the brain associated with insufficient oxygenation to support the metabolic requirements of the tissue. "The miR-766-3p/NR3C2 axis is participating in the protection against cerebral ischemia and reperfusion." (PMID 38650649, 2024). "The intersection target between cerebral ischemia and TB-12 was NR3C2." (PMID 39376614, 2024).
pseudohypoaldosteronism type 1 (8 papers, 2009 to 2024). A rare, primary form of mineralocorticoid resistance characterized by mild to profound salt wasting either restricted to the kidney (renal pseudohypoaldosteronism type 1), or generalized affecting many organs (generalized pseudohypoaldosteronism type 1). "Pseudohypoaldosteronism type 1 is a rare genetic disorder characterized by salt wasting and resistance to mineralocorticoids due to mutations in the NR3C2 gene which codes for the aldosterone receptor proteins in the kidneys." (PMID 38689677, 2024).
Sepsis (8 papers, 2012 to 2025). Sepsis is defined as life-threatening organ dysfunction caused by a dysregulated host response to infection. "NR3C2 participates in corticosteroid signaling, a process that is essential for modulating the inflammatory response observed in sepsis." (PMID 40765579, 2025). "In our model, four genes (NR3C2, CEACAM1, VNN1, and SLC2A3) were linked to the development of AKI in patients with sepsis." (PMID 40765579, 2025). "The upregulation of NR3C2 in the sepsis cohort suggests a compensatory mechanism designed to counteract the inflammatory milieu, which may have implications for therapeutic interventions targeting this receptor." (PMID 40765579, 2025). "Cortisol binds two receptors, the glucocorticoid (GR, NR3C1) and mineralocorticoid receptor (NR3C2), however, the GR is more relevant in responses to stress, sepsis and septic shock, and as such, the focus of this review." (PMID 39968295, 2025).
Cirrhosis (6 papers, 2020 to 2025). A chronic disorder of the liver in which liver tissue becomes scarred and is partially replaced by regenerative nodules and fibrotic tissue resulting in loss of liver function. "Although NR3C2 status in ACLF has not been explored, MR mRNA and protein expression were reduced in the hepatocytes of patients with cirrhosis and ascites." (PMID 33996909, 2021).
pseudohypoaldosteronism (6 papers, 2009 to 2024). An inherited or acquired disorder of electrolyte metabolism, characterized by the inability of the renal tubules to respond to aldosterone. "Nine patients were confirmed with aldosterone resistance, of which one child was diagnosed with pseudohypoaldosteronism (PHA) type 1 with a mutation in the NR3C2 gene and 3 children were identified with PHA type 2 due to novel mutations in either the CUL3 or KLHL3 genes." (PMID 36726778, 2023). "Corticosterone, 18−hydroxycorticosterone and aldosterone are elevated through renin/angiotensin stimulation in disorders of aldosterone receptor and the gene NR3C2 encoding the mineralocorticoid receptor can have mutations in some (pseudohypoaldosteronism − PHA)." (PMID 21274298, 2009). "This lack of response to mineralocorticoids was reminiscent of pseudohypoaldosteronism in humans and could not be explained by a decrease in mRNA expression of NR3C1 or NR3C2 in rice rat cultures." (PMID 31491720, 2019).
adenoma (5 papers, 2012 to 2024). A neoplasm arising from the epithelium. "Adenomas causing CD have higher expression of hsa-miR-124-3p and hsa-miR-135-5p and lower expression of their target genes NR3C1 and NR3C2." (PMID 35270010, 2022). "Compared with adenoma and normal epithelium, enhanced expression of NR3C2 was observed in epithelial tumor cells, which is in line with that in the Atlas database." (PMID 34094897, 2021). "For example, SPIB and NR3C2 were positively correlated with Module 1, indicating they are continuously inhibited during the mucosa-adenoma-carcinoma progression." (PMID 34094897, 2021). "Immunohistochemistry validation showed that GTF2IRD1 enhanced significantly throughout the mucosa-adenoma-carcinoma sequence, while SPIB and NR3C2 kept decreasing in stroma during the disease course." (PMID 34094897, 2021).
Alzheimer disease (5 papers, 2022 to 2025). A progressive, neurodegenerative disease characterized by loss of function and death of nerve cells in several areas of the brain leading to loss of cognitive function such as memory and language. "In GWAS studies, several SNPs of NR3C2 are associated with ASD hippocampal volume and Alzheimer’s disease." (PMID 40799755, 2025). "Furthermore, NR3C2 is one of the Alzheimer’s disease genes targeted by active compounds of the Bushen Tiansui Formula, such as icariin." (PMID 39456437, 2024).
clear cell renal cell carcinoma (5 papers, 2020 to 2023). "Downregulated NR3C2 expression is associated with a poor prognosis and aggressive characteristics in nondistant metastatic clear-cell renal cell carcinoma." (PMID 36829221, 2023). "For example, low NR3C2 expression was associated with poor prognosis in patients with nonmetastatic clear cell renal cell carcinoma and colon adenocarcinoma." (PMID 33564687, 2021).
glioblastoma (5 papers, 2014 to 2022). The most malignant astrocytic tumor (WHO grade IV). "NR3C2 acts as a tumor suppressor and inhibits the proliferation, migration, and invasion of several cancers, including pancreatic, breast, lung, and glioblastoma." (PMID 36358691, 2022). "As such, we studied the expression of the MR gene NR3C2 in a panel of glioblastoma cell lines a strictly linear correlation across all lines." (PMID 34769089, 2021).
neuroblastoma (5 papers, 2013 to 2023). Neuroblastoma (NB) is the most common solid, extracranial childhood tumor. "Indeed, we found that the transfection in neuroblastoma cells of miR-135a, that has two binding sites on the Nr3c2 3’ UTR, induces a strong suppression of the MR." (PMID 24023867, 2013).
colitis (4 papers, 2014 to 2025). Inflammation of the colon. "Several nuclear receptors were specifically downregulated in males (Vdr, Lrh1/Nr5a2, Mr/Nr3c2, Rev-erbβ/Nr1d2, Car/Nr1i3, Esrrg, Lxrα/Nr1h3) and have indeed been demonstrated to regulate key protective functions relating to colitis or CRC." (PMID 36142324, 2022).
preeclampsia (4 papers, 2023 to 2025). Preeclampsia is a hypertensive disorder of pregnancy that is characterized by new-onset hypertension with proteinuria presenting after 20 weeks of gestation, and depending on mild or severe forms may initially present with severe headache, visual disturbances, and hyperreflexia. "Abnormalities in NR3C2 effector mechanisms, particularly through maternal sodium (Na+) retention, have been shown to play a role in preeclampsia aetiology." (PMID 41444673, 2025). "Cardiac gene expression of Vcam, Edn1, Ccr2, Ctgf, Tgfb1, Tgfb2, Tgfb3, Bnp, Cybb, Mmp2, Mmp9, Timp1, Camk2a, Slc9a1, Nr3c2, and Nr3c1 was not different between mice who had a normal pregnancy and mice who had a preeclampsia-like pregnancy at 5 or 10 weeks postpartum (respectively)." (PMID 40425613, 2025).
renal dysfunction (4 papers, 2011 to 2025). "The odds of renal dysfunction were higher in variant carriers of PPP3CC rs10108011, PPP3CC rs2461494, and PRKAG2 rs7805747, whereas the odds of renal dysfunction were lower in variant carriers of CACNA1D rs893365 and NR3C2 rs1490453." (PMID 33868389, 2021).
schizophrenia (4 papers, 2018 to 2023). A major psychotic disorder characterized by abnormalities in the perception or expression of reality. "NR3C2, on the other hand, showed significantly increased methylation of the N3C2-4 region in females with schizophrenia, with no such correlation found in males." (PMID 37108291, 2023).
autism spectrum disorder (3 papers, 2022 to 2024). A spectrum of developmental disorders that includes autism, and Asperger syndrome. "Zebrafish models have already been useful for this purpose, for example validating nr3c2 as an autism spectrum disorder risk gene based on human whole-genome sequencing and zebrafish functional assays." (PMID 35465097, 2022). "Furthermore, mutations in NR3C2, the gene that encodes MR, are associated with autism spectrum disorder in humans, further strengthening the implications that MR dysregulation, and perhaps CA2, may be involved in some the behavioral deficits found in certain neurodevelopmental disorders." (PMID 38405991, 2024).
gastric cancer (3 papers, 2014 to 2025). A primary or metastatic malignant neoplasm involving the stomach. "The examination of quantitative polymerase chain reaction (qPCR) data demonstrated a substantial downregulation (p value < 0.0001) in the expression of SYNPO2, NR3C2, and CCL28 in gastric cancer tissue samples when compared to matched tumour margin samples." (PMID 38081950, 2023). "Quantitative polymerase chain reaction (qPCR) was used to examine the expression levels of SYNPO2, NR3C2, and CCL28 in a total of 24 gastric cancer samples and 24 margin samples." (PMID 38081950, 2023). "NR3C2, SYNPO2, and CCL28, three genes targeted by mir-21, were shown to be highly expressed in both stomach cancer and healthy tissues." (PMID 38081950, 2023).
Gordon syndrome (3 papers, 2021 to 2025). An extremely rare multiple congenital malformation syndrome characterized by congenital contractures of hand and feet with variable degrees of severity of camptodactyly, clubfoot and, less frequently, cleft palate. "Despite a family history suggesting Gordon syndrome, genetic testing revealed a unique Pro701Leu mutation in the NR3C2 gene." (PMID 40441250, 2025). "Although mutations in Kelch-like 3 and Cullin 3 are common in Gordon syndrome, finding a mutation in the MR gene, NR3C2, was unexpected." (PMID 40441250, 2025).
lung carcinoma (3 papers, 2013 to 2022). "We picked the top 5 genes (ZNF24, NR3C2, CST4, ARHGDIG and CRYBB3) to confirm their lung cancer suppressive function." (PMID 36457047, 2022).
pneumonia (3 papers, 2022 to 2025). An acute, acute and chronic, or chronic inflammation focally or diffusely affecting the lung parenchyma, caused by an infection in one or both of the lungs (by bacteria, viruses, fungi, or mycoplasma.). "We also found previously that a high-calorie diet will cause serum ACTH and CORT to decrease and expression levels of hypothalamus Nr3c1 and Nr3c2 proteins to decrease in juvenile rats with LPS-induced pneumonia." (PMID 40724811, 2025).
renal carcinoma (3 papers, 2021 to 2024). A carcinoma arising from the epithelium of the renal parenchyma or the renal pelvis. "NR3C2 was reported to inhibit the proliferation of renal cancer cells in vitro and in vivo." (PMID 36950803, 2023). "Contrary to our results, Ald was reported to promote the survival and proliferation of renal carcinoma cells co‐expressing hMR and 11βHSD2,33, 34 which may be due to the expression and the roles of NR3C2 varied in organs." (PMID 36950803, 2023). "NR3C2 has been described as a tumor suppressor in multiple malignancies, such as pancreatic, lung, colon, and renal cancers; however, the prognostic value and biological effect of low NR3C2 level in BC remains unclear." (PMID 33494738, 2021).
thyroid cancer (3 papers, 2013 to 2024). "We collected 47 classic variants of PTC, 9 hobnail variants of PTC, 3 anaplastic thyroid cancers (ATC), and 10 medullary thyroid cancers (MTC) to evaluate the differences in NR3C2 gene expression among aggressive thyroid cancers." (PMID 38255827, 2024).
asthma (2 papers, 2018 to 2021). "NR3C2 mRNA expression was also significantly downregulated in severe asthmatics compared to moderate asthma (log2 intensity 5.397 ± 0.727 versus 5.62 ± 0.5011, p < 0.01) and to healthy controls (log2 intensity 5.575 ± 0.5894 versus 5.397 ± 0.727, p = 0.03)." (PMID 34395637, 2021).
early onset hypertension (2 papers, 2010 to 2025). A form of hypertension with early onset relative to normal range for a given population. "Also, mutation in NR3C2 gene that alters the specificity of the receptor has been associated with autosomal dominant form of early-onset hypertension." (PMID 19944075, 2010).
glioma (2 papers, 2018 to 2021). A benign or malignant brain and spinal cord tumor that arises from glial cells (astrocytes, oligodendrocytes, ependymal cells). "The interrogation of patient data including high grade (GBM) and low grade (LGG) gliomas revealed that lower NR3C2 expression significantly associated with lower overall survival." (PMID 34769089, 2021). "In accordance with our results, analysis of expression data from the TCGA GBM cohort using the GlioVis data visualization tool revealed that NR3C2 expression is significantly reduced in glioma tumors compared to normal tissue." (PMID 34769089, 2021). "Accordingly, GBM samples showed significantly lower NR3C2 expression than low grade glioma subtypes oligodendroglioma and astrocytoma." (PMID 34769089, 2021). "Indeed, further analysis of NR3C2 expression in human glioma tumors showed that its expression significantly diminished with tumor grade." (PMID 34769089, 2021). "Indeed, grade IV gliomas (GBM) expressed the lowest levels of NR3C2, which could be observed in both the TCGA and Rembrandt cohorts." (PMID 34769089, 2021). "The fact that NR3C2 expression was significantly reduced in glioma tumors compared to normal tissue suggested that the expression of the MR was not beneficial for glioma development." (PMID 34769089, 2021).
hypothyroidism (2 papers, 2013 to 2019). Abnormally low levels of thyroid hormone. "Interestingly, the mineralocorticoid receptor NR3C2 gene has recently been found to be up-regulated in adult-onset hypothyroidism, and PDE8B and CAPZB have been suggestively associated with hypothyroidism by GWAS." (PMID 23408906, 2013).
injury (2 papers, 2020 to 2022). Damage inflicted on the body as the direct or indirect result of an external force, with or without disruption of structural continuity. "We investigated whether the genetic polymorphisms rs5522 and rs2070951 of NR3C2 showed main and interactive effects with childhood trauma on memory decline." (PMID 32558353, 2020).
liver cancer (2 papers, 2021 to 2023). An epithelial or non-epithelial malignant neoplasm that arises from the liver. "As the target gene of miR‐766, NR3C2 participated in the β‐catenin signalling pathway to inhibit the proliferation and metastasis of liver cancer cells." (PMID 36950803, 2023). "NR3C2 has also been shown to inhibit the proliferation and metastasis in SMMC‐7721 and HCCLM3 liver cancer cells, as well as 786‐O and ACHN kidney cancer cells." (PMID 36950803, 2023).